GPC3 (glypican 3)
Diseases named in the same sentence as GPC3 in open-access papers (continued):
Sharing a sentence is not in itself a finding about the gene and the disease.
tumor (continued). "The results indicated that high expression of GPC3 was closely correlated with high tumor grade, late TNM stage and the presence of vascular invasion." (PMID 24548704, 2014). "Glypican-3 Immunohistochemistry reveals positive staining in the tumor nodules, similarly to what happens in humans, and in the zone 3 of the parenchyma of damaged liver in the CDAA+CCl4 group." (PMID 24853141, 2014). "Our results demonstrated that GPC3-expression increases M1 macrophages in tumor mass, ascitic fluids and inguinal lymph node." (PMID 24992906, 2014). "High GPC3 expression tended to be correlated with high tumor grade (moderate and poor differentiation) in four studies, and a statistical significant correlation was observed in three studies." (PMID 24548704, 2014). "The FACS analysis showed that CD8+ T cells constituted 4.1% of the total lymphocytes in the GPC3-expressing tumor and 1.51% in the tumor formed by injection of the control HM-1 cells." (PMID 24992906, 2014). "Pooled data from all four studies showed a significant correlation between high GPC3 expression and high tumor grade (OR: 3.30, 95% CI: 2.04–5.33, p = 0.000)." (PMID 24548704, 2014). "Although it appears that DSF suppresses the tumorigenicity of tumor-initiating HCC cells in part by downregulating GPC3 expression, further analyses would be of importance to clarify the mechanisms underlying the downregulation of GPC3 by DSF." (PMID 24454751, 2014). "High GPC3 expression tended to be correlated with late tumor stage (III + IV) in 3 studies, and a statistical significant correlation was observed in two studies." (PMID 24548704, 2014). "MiR-219 has been found to be significantly downregulated in HCC, and exert tumor-suppressive effects in hepatic carcinogenesis through negative regulation of GPC3 expression, which is consistent with our experimental results in HCC cell lines and tissues." (PMID 24980149, 2014). "The cut-off values of high GPC3 expression were 0%, 10%, 20%, and 25% of positive tumor cells by IHC staining reported in the included studies, respectively." (PMID 24548704, 2014). "Pooled data from all four studies showed high GPC3 expression tended to be correlated with the tumor size ≥ 5 cm (OR: 1.30, 95% CI: 0.88–1.93, p = 0.19)." (PMID 24548704, 2014). "Further studies are required to verify the prognostic significance of serum-based GPC3 levels, as a simple method to monitor response to systemic therapy, tumor progression and prognosis." (PMID 24548704, 2014). "Pooled data from all four studies showed high GPC3 expression tended to be correlated with the presence of tumor multifocality (OR: 2.42, 95% CI: 0.94–6.23, p = 0.07)." (PMID 24548704, 2014). "The percentage of infiltrating CD86+/F4/80+ cells in the GPC3-expressing tumor was approximately 15.93% in the region of monocytes and macrophages, whereas it was only 5% in the control tumors." (PMID 24992906, 2014). "According to our analysis, GPC3 expression significantly increased the proportion of M1 macrophages in tumor mass and ascitic fluids." (PMID 24992906, 2014). "Among the upregulated genes, PGC, AFP, AKR1B10 and GPC3 showed more than 30-fold increased expression in the HCC tumor group." (PMID 25217841, 2014). "High GPC3 expression tended to be correlated with the presence of tumor multifocality in two studies." (PMID 24548704, 2014). "In contrast, the stable overexpression of GPC3 promoted cell growth and sphere formation of tumor-initiating HCC cells." (PMID 24454751, 2014). "miR-219 has been shown to exert tumor-suppressive effects during hepatic carcinogenesis through negative regulation of GPC3 expression." (PMID 24980149, 2014). "Collectively, we suggest that GPC3 expression recruits M1 macrophages to engulf cancer cells and enhances antigen presentation ability to lymphocytes, and then induces GPC3-specific T cell-mediated immune response to suppress GPC3-expressing tumor growth." (PMID 24992906, 2014).
tumor (continued). "shRNA1 downregulated GPC-3 expression to suppress tumor cell proliferation and had a synergistic effect with chemotherapy drug." (PMID 23192642, 2013). "We are analyzing theTCRgene sequences of CD8 or GPC3 dextramer positive T cells in both the peripheral blood and tumor." (PMID 23903757, 2013). "More recently, glypican-3 also became a potential and reliable biomarker for predicting tumor recurrence and overall survival in HCC patients after curative resection." (PMID 23984412, 2013). "Our aim is to reveal the GPC3 peptide-specific immune responses induced by the GPC3-derived peptide vaccine in both the peripheral blood and the tumor." (PMID 23903757, 2013). "miR-219-5p exerted tumor-suppressive effects in hepatic carcinogenesis through negative regulation of GPC3 expression in vitro." (PMID 22922800, 2012). "The tumour cells have an epithelial histology and express HCC-associated proteins such as Alpha-fetoprotein (AFP), Glypican 3, E-cadherin, CD10, CD326, HepPar1 and Vimentin." (PMID 22666492, 2012). "In normal situation, GPC-3 is involved in the regulation of cell proliferation and survival during embryonic development and plays a crucial role as a tumor suppressor." (PMID 23162601, 2012). "GPC3 mRNA was upregulated significantly in tumor tissues of HCC compared to paraneoplastic liver tissue, liver tissues of healthy adults, and liver tissues of patients with nonmalignant hepatopathy." (PMID 22655201, 2012). "Glypican-3 (GPC3), a heparan-sulfate proteoglycan, has recently been identified as a highly specific, membrane-associated tumor antigen found in 49-100% of HCC." (PMID 22564378, 2012). "The level of glypican-3 and survivin in cell lysate was elevated after test tumor cells were treated with colchicine, CMQ, FMQ or doxorubicin." (PMID 21689407, 2011). "The marker genes Myc, Glul and Oat presented pre-tumor-specific differential expression which was reverted in the tumor state, whereas Ccnd1, Gpc3, Mvk, Pparg, Rbl2, Robo1 were only upregulated in tumors." (PMID 21464922, 2011). "Tumours with K19 expression was found in twelve percent of the tumours and were correlated with glypican-3 (marker of malignant change) expression and increased malignancy based on histological grading and staging of the tumours." (PMID 20167095, 2010). "GPC3 was suggested as a possible tumor marker for HCC, since the levels of GPC3 were significantly high in the serum of HCC patients, but undetectable in healthy donors and patients with benign liver diseases." (PMID 24281095, 2010). "Southern blot- and PCR-based methylation assays were used to assess the methylation status of the GPC3 promoter on genomic DNA from both normal and embryonal tumour cells." (PMID 15083193, 2004). "To investigate this possibility we have analysed an unselected series of WT cases, for the presence of somatic and constitutional alterations to GPC3 in tumour and normal tissue respectively." (PMID 12085187, 2002). "To explore the potential impact of GPC3 isoforms on anti-tumor efficacies, we first compared the sequence information of four GPC3 variants (NM_001164617.2, NM_004484.4, NM_001164618.2, and NM_001164619.2), which have been identified in GenBank and encode alternatively spliced forms." (PMID 39841705, 2025). "Ultra large porous silica nano-depot (UPSND) was used to deliver Cas9 and sgRNA for GPC3 in a Hepa1-6 mouse orthotopic allograft model demonstrating efficient inhibition of Wnt and Hippo signaling, complete tumor eradication and T cell infiltration in the tumor." (PMID 41300975, 2025). "Furthermore, the GPC3 CRISPR‐Cas9@UPSND treatment exhibits superior anti‐proliferative efficacy in tumor‐growth prevention compared to Codrituzumab, as evidenced by the analysis of Ki67 and GPC3 expression, along with serum GPC3 levels." (PMID 40657181, 2025).
tumor (continued). "In contrast to hematologic malignancies, where lineage-specific markers such as CD19 and BCMA offer consistent targeting, many solid tumor-associated antigens (e.g., mesothelin, B7-H3, GPC3) are variably expressed and are not uniformly tumor-specific." (PMID 40723278, 2025). "Notably, GPC3 is found to be highly expressed in tumour tissue samples from approximately 70% of HCC patients." (PMID 41267637, 2025). "Although molecular profiling (e.g., CTNNB1 or TERT promoter mutations) was not available, the tumour's strong beta-catenin and Glypican-3 expression supported a diagnosis of HCC." (PMID 41583252, 2025). "SN Huang discovered that the GPC3 scFv engineered and IR780-loaded exosomes (IR780@GPC3-EXOs) could quickly target HCC and cause notable tumor suppression by photothermal effects after near infrared (NIR) light." (PMID 41567219, 2025). "Similarly, in NSCLC, CAR T-cell therapy is being developed to target tumor-specific antigens, such as GPC3, PD-L1, and CD80/CD86, aiming to bypass resistance mechanisms and improve patient outcomes." (PMID 40094890, 2025). "Patients were categorized according to GPC3 expression in tumor tissue." (PMID 41463223, 2025). "At Day 7 post‐tumour implantation, the tumour size reached the therapeutic window of 50–100 mm3, and 5 × 106 anti‐GPC3 (9F2) CAR‐T cells were administered either intravenously via the tail vein (t.v.)or intratumourally (i.t.)into the tumour xenografts (red arrow)." (PMID 41267637, 2025). "Given that GPC3 is a membrane-bound proteoglycan and a target for emerging immunotherapies, membranous expression may mark a more aggressive tumor phenotype that is less responsive to immune checkpoint and anti-angiogenic therapies." (PMID 41463223, 2025). "A phase I clinical trial of the anti-GPC3 monoclonal antibodies, codrituzumab combined with atezolizumab, demonstrated not only good tolerance of the agents but also significant suppression of tumor growth in patients with advanced HCC." (PMID 40941632, 2025). "We systematically evaluate conventional markers, such as hepatocyte paraffin 1 (HepPar1), arginase-1 (Arg-1), and glypican-3 (GPC3), as well as emerging biomarkers, detailing their diagnostic sensitivities and specificities in HCC with varied tumor differentiation." (PMID 40941632, 2025). "However, the AUC of the GDATA model for diagnosing early HCC was significantly higher than that of single tumor markers GPC3, AFP, AFP-L3% and DCP, indicating that the GDATA model has a higher discriminatory ability in the diagnosis of early HCC." (PMID 41471145, 2025). "Preclinical efficacy in murine xenograft models may not accurately predict human outcomes due to differences in the tumor microenvironment, immune contexture, and GPC3 expression levels between models and patients." (PMID 40722645, 2025). "BC2027 is a first-in-class ADC targeting GPC3 that, as of April 2024, received FDA clearance for in-human studies in GPC3-positive cancers after demonstrating in preclinical studies greater than 90% inhibition of tumor growth in some well-established GPC3-positive cancers." (PMID 39858016, 2025). "GPC3 also interacts with the Hedgehog signaling pathway, potentially acting as a competitive inhibitor of Hedgehog ligand binding, thus exerting complex and context-dependent regulatory effects on tumor progression." (PMID 40722645, 2025). "Notably, GPC3 expression correlates with poor prognosis, aggressive tumor features, and shorter disease-free survival after curative treatment." (PMID 40722645, 2025). "Consequently, the combination of SRF, anti-miRNA 27a, and anti-GPC3 antibodies led to enhanced apoptosis, reduced tumor volume by nearly threefold compared to control, and significant tumor accumulation than in normal tissue." (PMID 40880603, 2025).
tumor (continued). "Furthermore, the dual-targeting strategy utilizing anti-VCAM1 mAbs and anti-GPC3 mAbs enhances the specificity and sensitivity of therapy toward both CTCs and primary tumor cells, thereby improving overall therapeutic outcomes." (PMID 40528159, 2025). "Tumor cell positivity for glypican-3 and AFP supported yolk sac differentiation." (PMID 41510478, 2025). "These include dual-target CARs that require recognition of two tumor-associated antigens (e.g., B7-H3 and GPC3, or EGFRvIII and mesothelin) or use AND-/NOT-gating logic to fine-tune activation thresholds." (PMID 40723278, 2025). "Its tumor-restricted distribution and functional role in key oncogenic pathways—such as Wnt/β-catenin, Hedgehog, and fibroblast growth factor signaling—have established GPC3 as a highly promising biomarker for both imaging and therapy." (PMID 40722645, 2025). "CARs were studied that target various tumor antigens such as the B cell maturation antigen (BCMA), CD19, disialoganglioside GD2 (GD2), glypican-3 (GPC3) and epidermal growth factor receptor variant III (EGFRvIII), and contain different costimulatory domains including CD28 and 4-1BB 24–28." (PMID 38744947, 2025). "Finally, utilizing GPC3 as a vehicle for optimal tumor-specific immune targeting is an area of clinical therapeutic development to watch." (PMID 39858016, 2025). "In cancers, the intrinsic factors of the tumor cells, such as genetic background, tissue origin, gene expression profile, etc., may influence the functional manifestation of GPC3." (PMID 40422229, 2025). "In addition, DC vaccines loaded with specific antigens such as AFP, MAGE-1, and GPC-3 enhanced IFN-γ-generating CTL responses against tumor antigens in trials combining TACE or surgical resection." (PMID 40432108, 2025). "In this context, GPC3 may provide complementary information, reflecting both tumor biology and potential eligibility for GPC3-directed therapies." (PMID 41463223, 2025). "UPSND‐loaded with human sgRNA not only demonstrated effective in vivo gene editing in human HCC but also, when compared to monoclonal antibody drugs targeting GPC3, revealed that complete gene excision offers superior tumor suppression compared to mere physical blockade." (PMID 40657181, 2025). "In addition, GPC3 expression levels were further increased in drug-resistant tumor cell lines, suggesting its potential role in cancer cell drug resistance." (PMID 40422229, 2025). "EGFRvIII/GPC3-targeting CARs have been induced in pluripotent stem cell-derived macrophages that demonstrated improved antitumor effect through M1 polarization, tumor cell phagocytosis, and apoptotic tumor cell efferocytosis." (PMID 40647477, 2025). "Furthermore, the radiolabeled analog [18F]AlF-NOTA-TJ12P2 was found to display specific accumulation in GPC3-expressing tumors as well as tumor-to-liver contrasts of up to 2.85, rendering this peptide promising for further clinical translation." (PMID 41304901, 2025). "Baseline characteristics, including age, sex, underlying liver function, and tumor stage, were well balanced between the GPC3-positive and GPC3-negative cohorts, minimizing confounding due to baseline imbalances." (PMID 41463223, 2025). "The resulting GPC-3.CAR/sIL-15 Vδ1 T cells demonstrated a less differentiated phenotype, expressing tissue-homing markers and chemokine receptors associated with efficient trafficking to tumor sites." (PMID 38338658, 2024). "Furthermore, ERY974, a type of BiTE that targets glypican-3, significantly increased T cell infiltration and induced tumor regression when combined with chemotherapy." (PMID 38752985, 2024). "The CAR-NK cells also showed tumor-specific accumulation and induced apoptosis in GPC3-positive tumors without causing evident tissue damage in other organs." (PMID 38694508, 2024). "GPC3 andMUC13 were co-expressed in approximately 40% of tumor cells." (PMID 39872360, 2024).
tumor (continued). "Our test using ICG to identify CTCs may be more widely applicable to other tumors that accumulate ICG, and our panel could be easily adapted to these tumors by substituting GPC3 with alternative tumor-specific markers." (PMID 38727682, 2024). "Notably, these engineered cells exhibited robust in vitro antitumor activity against GPC-3-expressing tumor cell lines, even in the presence of soluble GPC-3." (PMID 38338658, 2024). "Although a large proportion of tumour cells were found along this Dlk1/Gpc3/Afphi branch, there were a small but substantial number of tumour cells along Notch1/Tgfb1hi branch 2, which was characterized by another progenitor and stem marker: Nes (which encodes nestin)." (PMID 39112713, 2024). "In our study, GPC3 expression was detected in tumor tissue of all 13 OCCC patients." (PMID 38824600, 2024). "Furthermore, in vivo experiments demonstrated the enhanced antitumor activity of GPC-3.CAR/sIL-15 Vδ1 T cells in a xenograft tumor model, showcasing their potential for clinical application without inducing xenogeneic GVHD." (PMID 38338658, 2024). "Thus, the Dlk1+/Gpc3+/Afp+ progenitor-like cells potentially represent a tumour-initiating state for branch 1 tumours." (PMID 39112713, 2024). "Several promising CAR-T cell tumor targets were identified, including Glypican-3 (GPC3), alpha-fetoprotein (AFP), NK group 2 member D ligand (NKG2DL), Mucin 1 glycoprotein 1 (MUC1), Epithelial cell adhesion molecule (EpCAM), Claudin18.2 (CLD18), CD147, CD133, HBV surface protein, and c-MET." (PMID 36980692, 2023). "Finally, we investigated the therapeutic efficiency of G-NK cells against glypican-3+ tumor cells in vivo." (PMID 37665421, 2023). "Moreover, to evaluate the killing effect of CTLs on TYST, the levels of GPC3 and granzyme B expression were also determined by IHC in tumor tissues." (PMID 37986544, 2023). "Immunohistochemical analysis of the tumor tissue was positive for Glypican-3 and AFP expression." (PMID 36805679, 2023). "Furthermore, treatment with GPC3144‐152 peptide, together with adoptive transfer of CD8+ T cells, inhibited the growth of TYST tumors, attenuating GPC3 expression and enhancing tumor cell apoptosis in mice." (PMID 37986544, 2023). "GPC3 expression on HCC tumor cells is correlated with a poor prognosis in HCC." (PMID 37048069, 2023). "The GPC3 molecule on the surface of HepG2 cells can mediate the endocytosis of NPs, so that the cells can more effectively enrich mAb-modified NPs and exert a higher tumor suppressor effect." (PMID 37919282, 2023). "Therefore, most HCC patients who have received prior systemic therapy are likely to express GPC3 on their tumor cells." (PMID 37048069, 2023). "In this study, patients with GPC3-positive HCC predominantly showed irregular tumor margins, which may be due to the higher malignancy of GPC3-positive HCC and the susceptibility of tumor marginal tissues to invasion, resulting in changes in morphology." (PMID 37841420, 2023). "In addition, elevated serum AFP levels were observed to be positively correlated with the poor differentiation, microvascular invasion and tumor recurrence, which is consistent with the biological behavior of GPC3-positive HCCs." (PMID 38023195, 2023). "For GC, previous study report GPC3 expression is markedly decreased and may play a tumour suppressor role in GC." (PMID 37036308, 2023). "The specific expression of GPC3 in tumour cells has received much attention." (PMID 36930359, 2023).